CTLA4 (cytotoxic T-lymphocyte associated protein 4)
Diseases named in the same sentence as CTLA4 in open-access papers (continued):
Sharing a sentence is not in itself a finding about the gene and the disease.
tumor (continued). "They found that the anti-CTLA-4 allowed a tumor control which is abrogated in case of local treatment of the lymph node areas by surgery or RT." (PMID 37539054, 2023). "For example, immune checkpoint inhibitors targeting CTLA-4 and PD-1/PD-L1 have revolutionized cancer treatment by inducing and restoring anti-tumor immunity." (PMID 36992198, 2023). "In pre-clinical studies, radiation enhanced the diversity of the T-cell receptor (TCR) repertoire of intratumoral T cells, while anti-CTLA4 promoted T cell expansion in the tumor and peripheral blood." (PMID 37620372, 2023). "Immune checkpoint inhibitors, including PD-1, PD-L1, and CTLA4, inhibit the tumor’s division, growth, and invasion by affecting the immune response of the tumor." (PMID 37350946, 2023). "Of nine PDTCs treated with the triple combination (i.e., NILK-2301 + PD-1 inhibitor nivolumab + CTLA-4 inhibitor ipilimumab), six had a reduction of tumor vitality (67%)." (PMID 38087365, 2023). "Although we have restricted our analysis to lymphocytes, we know that Notch signaling can also affect other factors such as tumor associated fibroblasts, endothelial cells and the expression of CTLA4 in tumor infiltrating lymphocytes." (PMID 36925919, 2023). "Through peritumoral injection of the DOX/anti-CTLA-4/anti-PD-1 co-loaded hydrogel into melanoma-bearing C57BL/6 mice, the ICD of tumor cells by DOX release caused the release of DAMPs and TAAs, which can promote the activation of DCs." (PMID 37265604, 2023). "In the same model, combination therapy with anti-PD-1 and anti-CTLA-4 induced substantial tumor growth inhibition, which was further enhanced by anti-IL-34 treatment." (PMID 36765929, 2023). "Currently, a first clinical CTLA-4 imaging study is ongoing, where tumor lesion uptake and the biodistribution of 89Zr-labeled ipilimumab will be assessed at the start of ipilimumab therapy and after the second injection three weeks later." (PMID 36674595, 2023). "This study first proposed the concept of the ICI and provided experimental animal evidence that the CTLA-4 antibody can enhance the anti-tumor immune response." (PMID 36604694, 2023). "Dual targeting of both innate and adaptive checkpoints is theoretically attractive, also since data suggest that dual targeting of discrete checkpoints, e.g. CD47, PD1/PD-L1 or CTLA4, can be synergistic with regard to their anti-tumor effects." (PMID 37012357, 2023). "In pre-clinical studies, radiotherapy combined with PD-1, PD-L1, and CTLA-4 inhibitors improved long-term survival and prevented tumor recurrence under a variety of fractionated doses." (PMID 37403111, 2023). "Immune checkpoints, especially PD-1 and CTLA4, are involved in tumor immune escape by generating inhibitory signals that suppress the activation or proliferation of some immune cells." (PMID 37059591, 2023). "This is why anti‐PD1L and anti‐CTLA‐4 antibodies have a therapeutic effect in tumour patients, in particular when applied in combination with cell death‐promoting agents, likely by enhancing immunological cell death." (PMID 36861295, 2023). "Ipilimumab, currently the sole FDA-approved CTLA4 inhibitor, promotes massive T cell proliferation and combats tumor cells by preventing CTLA4 from binding to its B7 molecular ligand." (PMID 37798374, 2023). "In cancer patients, tumor cells exploit this immune checkpoint by the constitutive expression of CTLA4, which binds to the B7 molecule and blocks the costimulatory signal, thereby inhibiting T cell activation." (PMID 36831044, 2023). "The incorporation of anti-PD1 and anti-CTLA-4 into the TME of intact tumor fragments had mixed overall effects on the TILs." (PMID 37359554, 2023). "First, the expression of genes associated with tumor-infiltrating Tregs such as CTLA4, GITR, LAYN and OX40 was significantly higher in tumor tissues compared to non-tumor tissues." (PMID 37313417, 2023).
tumor (continued). "The identification of immune “checkpoints” (PD-1/CTLA-4) whose blockade stimulates anti-tumor immunity has changed outcomes for many ptients." (PMID 36980777, 2023). "In the immediate vaccine model, CD24-Fc or human IgG-Fc control was injected simultaneously with the whole cell vaccine plus anti-PD-L1/CTLA4 antibodies at day 7, 10 and 13 post tumor inoculation." (PMID 37346042, 2023). "­Anti-tumour activity leads to upregulation of immune checkpoints such as PD-1 and CTLA-4 on T-cells which leads to T-cell anergy and immunosuppression." (PMID 37599903, 2023). "Similar to the previous experiment, the combined effects of treating tumor-bearing mice with opaganib and anti-CTLA-4 antibody were examined in the LLC tumor model." (PMID 38069222, 2023). "It was found that the in vivo tumor inhibition efficacy and antitumor immune response can be further augmented by the incorporation of anti-PD-1 and/or anti-CTLA-4." (PMID 37265604, 2023). "There is also marked upregulation of immunosuppressive molecules such as CTLA-4 and DcR3 that attenuates anti-tumor immunity." (PMID 37762648, 2023). "Immune checkpoint inhibitors are commonly used immunotherapy medications that boost the cytotoxicity and proliferation ability of tumor-infiltrating lymphocytes by blocking the binding of inhibitory receptors (including CTLA-4 and PD-1)." (PMID 37671167, 2023). "OX40, like CTLA-4, is significantly up-regulated on activated T cells in the tumor microenvironment (TME), particularly on Tregs." (PMID 37441075, 2023). "Chemokines secreted by solid tumors are usually not suitable for T cell infiltration; 2) Activation obstacle: Immune checkpoints such as PD-1, TIM-3, and CTLA-4 will be upregulated once CAR-T cells bind to tumor cells, thereby inhibiting immune responses." (PMID 38312512, 2023). "This dampening in the effect of CTLA-4 blockade in aged mice was also seen in the tumor growth rate analysis, where the fold change in growth rate compared to the untreated group was significantly less pronounced in the aged mice (p=0.0104)." (PMID 37920465, 2023). "It’s worth noting that the TIDE algorithm primarily predicts the responses to anti-PD1 and anti-CTLA4 treatments in tumor patients, thus making pembrolizumab a more suitable candidate for follow-up studies." (PMID 37207166, 2023). "Traditionally, it is believed that anti-CTLA-4 antibodies produces anti-tumor effect through blocking the interaction of CTLA-4/B7." (PMID 36895477, 2023). "CTLA4 is a prominent molecule in tumor immunotherapy, and antibody drugs targeting CTLA4 have emerged as a promising direction for anti-tumor therapy." (PMID 37798374, 2023). "To identify the target genes that regulate CTLA4 in TN-BCSCs, we initially performed tumor tissue clustering in TNBC." (PMID 37838657, 2023). "The major tumor-extrinsic mechanism is compensation for PD-L1/PD-1 and/or CTLA-4/CD80/86 blockade through alternate immune checkpoints such as LAG-3, TIM-3, TIGIT, and VISTA." (PMID 37444422, 2023). "Anti-CTLA-4 antibody enhances the immune response of the immune system, enabling T cells to more effectively attack tumor cells." (PMID 37860188, 2023). "In contrast, T cells carrying a TCR found exclusively in the tumour were enriched for exhaustion markers (CTLA4) and regulatory genes (FOXP3, TNFRSF4)." (PMID 38030622, 2023). "The interactions between the ITIM containing receptors and their ligands including but not limited to PD-1/PD-L1 and CTLA-4/CD80/86, are known to be involved in tumor development as well as loss of immune regulation." (PMID 36960400, 2023). "Early clinical trials suggest that these more specialized immune checkpoints namely LAG-3 in combination with PD-1 blockade exhibit a superior safety profile compared with PD-1 plus CTLA-4 blockade with equivocal anti-tumor activity." (PMID 37520544, 2023).
tumor (continued). "HIF-1α also stimulates the expression of the immune checkpoint inhibitors PD-L1, CTLA-4, and LAG-3 on tumor and tumor-associated immune and stromal cells." (PMID 37239368, 2023). "Results revealed that treatment with plant-produced anti-CTLA-4 significantly repressed tumor weight (TGITW = 96.93%) similarly to that of Yervoy®-treated group (TGITW = 99.20%)." (PMID 37711295, 2023). "CTLA-4 has been detected on tumor infiltrating NK cells in mice but has yet to be looked at in humans so further studies are needed to assess the benefit of combined CTLA-4 blockade and NK cell-based therapy." (PMID 37424864, 2023). "Functionally, highly activated circulating and tumor-infiltrating PD-1 + effector Treg cells show higher CTLA-4 expression levels than PD-1- effector Treg cells." (PMID 37143088, 2023). "At present, the effect of m6A modified tumor glycolysis on the treatment of tumor immune checkpoints inhibitors (anti-PD-L1/anti-PD-1 and anti-CTLA-4) has attracted people’s attention." (PMID 37582735, 2023). "iCAR typically fuses scFv recognizing a non-tumor antigen to the intracellular domain of an immune checkpoint molecule such as CTLA-4 or PD-1." (PMID 37596653, 2023). "Combined IL-6 and CTLA-4 blockade supports Th1 cytokines that crosstalk to facilitate chemokine production from tumor cells." (PMID 36881480, 2023). "Anti-CTLA-4 antibodies enhance tumor cell killing by blocking the CTLA-4-B7 checkpoint pathway or by selectively depleting Treg cells, although this requires further validation." (PMID 36612317, 2023). "Tremelimumab is a CTLA-4-targeted humanized IgG2 monoclonal antibody, which inhibits tumor growth by preventing the interaction between CTLA-4 and B7s and thereby allowing T-cell activation." (PMID 37415164, 2023). "Immune-cold tumor microenvironments are known to be characterized by low levels of PD-L1 and CTLA4 coupled with enhanced VTCN1 expression." (PMID 37388735, 2023). "Triple combination (anti-PD-1, anti-RANKL, and anti-CTLA-4 antibodies) was more effective in suppressing established tumor growth than dual therapy." (PMID 37929901, 2023). "A greater TIDE score suggests a higher probability of tumor immune escape and lower likelihood of benefitting from anti-PD-1/CTLA4 therapy, illustrating that high-ICDRS patients are candidates for ICB therapy." (PMID 37553698, 2023). "The frequency of circulating CD45+CTLA-4+ cells positively correlated with a subsequent poor response to neoadjuvant treatment determined by the Mandard tumour regression grade (TRG) scoring system." (PMID 36445478, 2023). "Addition of the anti-Ly6G antibody to anti-CTLA-4 and anti-PD-1 antibodies significantly accelerated tumor growth and weakened the dual-ICI response in both models." (PMID 37525015, 2023). "Tumor infiltrating lymphocytes with high co‐inhibitory receptor expression such as CTLA4, PD‐1, and LAG3 have been regarded as functionally exhausted rather than activated." (PMID 37789961, 2023). "VEGF contributes to tumor angiogenesis and upregulates immune checkpoint molecules (PD-1, PD-L1, CTLA4 and LAG-3)." (PMID 36765821, 2023). "We first determined the expression pattern of PD-1 and CTLA-4 on intratumoral T cell populations in tumor-bearing KEP mice." (PMID 37089449, 2023). "Ipilimumab is a monoclonal antibody against cytotoxic T lymphocyte antigen-4 (CTLA-4), which is another mechanism for immune escape by tumor cells." (PMID 37046621, 2023). "It was expected that tumor samples from these individuals would have a positive immune response to either PD-1/PD-L1 or CTLA4 inhibitors, or both." (PMID 36776843, 2023). "In a Lewis lung carcinoma mouse model, the use of an anti-CTLA-4 antibody led to an enhancement of the anti-tumor activity of irradiation by delaying tumor growth and prolonging mice survival." (PMID 37443821, 2023). "In the IRGPI-high group, the abundance of immune infiltrating cells in the tumor microenvironment is low and the expression of CTLA-4 is increased." (PMID 37322434, 2023).
tumor (continued). "Here the authors provide immunological insights into the response to RT and CTLA4 inhibition in tumor bearing mice and show that agonistic CD40 therapy improves response to the combination of RT and immune checkpoint inhibition." (PMID 37620372, 2023). "Treatment targeting immune checkpoints, such as anti-PD-1, anti-PD-L1, and anti-CTLA4 demonstrate impressive anti-tumor activities against several tumor types." (PMID 37520574, 2023). "Eradication of poorly immunogenic B16 tumours following anti-CTLA-4 blockade was only possible in a synergistic approach using a GM-CSF tumour vaccination." (PMID 37454231, 2023). "Different from CTLA4, Teffs in tumor express PD-1 at baseline or higher levels compared to tumor-infiltrating Tregs, potentially indicating exhaustion status." (PMID 37182149, 2023). "Such as PD-1 and CTLA-4, expressed on activated T cells lead to inhibition of T-cell activation upon binding to their ligands on tumor cells/antigen-presenting cells." (PMID 36859386, 2023). "The expression of PD-1, PD-L1, and CTLA4 between tumor tissue and normal tissue was also explored via the “limma” R package." (PMID 37251440, 2023). "The interaction of CD80 with CTLA-4 on T cell subsets can enhance the immune response against tumor cells by inactivating the tumor microenvironment." (PMID 37305822, 2023). "In animal models, application of gemcitabine with anti-CTLA-4 antibody showed improved survival compared to the monotherapy with each drug separately, predominantly through the induction of anti-tumour immune responses." (PMID 37760457, 2023). "The risk ratings delineated by this signature were tightly associated with tumor staging grades, TNBC subtypes, and the benefit of CTLA4 and PD-1-targeted therapies." (PMID 37928550, 2023). "Anti-CTLA-4 antibodies have been found to enhance the anticancer immune response and deplete tumor-infiltrating Tregs by means of antibody-dependent cell-mediated cytotoxicity." (PMID 37189748, 2023). "Second, CTLA-4 blockade depletes immunosuppressive regulatory T cells in the tumor microenvironment." (PMID 35864269, 2023). "Tumor immunotherapy is an important means, and a series of immune genes with great clinical potential have been discovered (PD-1, CTLA-4), longer OS for some patients." (PMID 36447119, 2023). "It was observed that the SDT-mediated depletion of total tumour volume coincided with changes in the proportions of different tumour-infiltrating Treg subsets and their CTLA-4 expression (respectively)." (PMID 36319895, 2023). "Triple blockade of Ly6C, PD-1, and CTLA-4 resulted in complete tumor responses, thus precluding further analysis of tumor tissues to explore the underlying mechanism of response." (PMID 37449205, 2023). "Activation of the Wnt/β-catenin pathway in solid tumors prevents T cells spontaneous activation and infiltration into the tumor microenvironment, increasing resistance to immune checkpoint inhibitor (PD-1 and CTLA4) therapy." (PMID 37658376, 2023). "Coinhibitory signals become hyperactivated because of overexpressed CTLA-4 in cytotoxic T cells or Treg cells induced by tumors, and overexpressed PD-L1 on tumor cells." (PMID 37926852, 2023). "Immune checkpoint inhibitors (ICIs), which target immunosuppressive receptors such as CTLA-4 and PD-1 to improve the cytotoxicity and proliferative potential of tumor-infiltrating lymphocytes (TILs), are among the most effective immunotherapeutics." (PMID 36900322, 2023). "Tumor cells escape the immune system by binding to CTLA-4 or PD-1, promoting the differentiation and activity of Treg cells and suppressing the growth and activity of effector T cells." (PMID 38203661, 2023). "In summary, the major function of the anti-CTLA-4 is to allow T-cell activation, proliferation, and migration to the tumor tissue mediating the death of tumor cells." (PMID 36835456, 2023).
tumor (continued). "For example, certain clinical trials using primary T cells with TCR- and/or HLA-knockout are known to diminish the alloreactivity of T cells, whereas PD-1- or CTLA-4 knockout can overcome immunosuppression of the tumour microenvironment." (PMID 36509913, 2023). "As early as 1996, one study showed that when mice with pre-established tumors were injected with anti-CTLA-4 antibody, tumor growth was reduced significantly." (PMID 36829496, 2023). "Tumor cells can evade detection of the immune system through various checkpoints, including cytotoxic T lymphocyte protein 4 (CTLA4), PD1 and PDL1." (PMID 37669923, 2023). "Immune checkpoint inhibitors function by addressing the overexpression of immune checkpoint molecules such as CTLA4, PD-1, and PD-L1 in the tumor microenvironment." (PMID 37600802, 2023). "Apart from the type and number of TILs, the expression of immune checkpoint genes on tumor cells, such as PD-L1 and CTLA-4, have been reported as predictive biomarkers for the therapeutic efficacy of immune checkpoint inhibitors in some cancers." (PMID 37569287, 2023). "Both tumor infiltrating lymphocytes and HNSCCs displayed a heterogeneous CTLA-4 protein expression pattern." (PMID 37415208, 2023). "A crucial mechanism by which tumors can escape the anti-tumor immune response is enhanced signaling of the programmed cell death protein 1 (PD-1)/cytotoxic T-lymphocyte antigen-4 (CTLA-4) pathway." (PMID 38136311, 2023). "Specifically, the BST2 gene signature predicted a response to a CTLA4 antibody called ipilimumab, suggesting a mechanistic involvement in tumor progression." (PMID 37414767, 2023). "CTLA-4 expressed on T cells blunts the immune system's response to tumor antigens by blocking binding of B7 on antigen-presenting cells (APC) to CD28 on T cells, resulting in suppression of APC function and impaired activation of CD8+ T cells." (PMID 37484200, 2023). "Although some studies have shown that blockade of CTLA-4 can lead to tumor regression in vitro using cell lines, the in vivo effects of CTLA-4 inhibition for UC have not been well studied." (PMID 38201559, 2023). "Vétizou and colleagues found that B. fragilis induced a TH1 phenotype, which led to restoration of treatment responsiveness to CTLA4 blockade in tumour-bearing germ-free mice." (PMID 37198490, 2023). "Our study also observed that infiltrating M2 macrophages and regulatory T cells were notably elevated in the group with CTLA4 high expression, indicating that CTLA4 promoted tumor growth by facilitating immune escape." (PMID 36397666, 2023). "On the other hand, and like traNK cells, small fractions of trNK cells in the primary tumor environment express fewer iKIRs, PD-1 and CTLA-4 cells, with the co-expression of >2 inhibitory receptors in less that 20% of the subset." (PMID 37444472, 2023). "Studies have exhibited promising outcomes concerning the DC-tumor fusion vaccine therapy of diverse cancer types through the blockade of CTLA-4, which signifies that targeting immune inhibitory molecules is able to impede T cell-mediated antitumor immunity." (PMID 37419930, 2023). "Immune checkpoints, such as programmed cell death protein 1 (PD-1) and cytotoxic T-lymphocyte-associated protein 4 (CTLA-4), regulate the activity of immune cells and can impact tumor immune evasion." (PMID 37465363, 2023). "Results obtained from single and multiplex immunohistochemical staining revealed significantly lower levels of immune cell infiltration and expression of PD1, TIM3, TIGIT, LAG3, and CTLA4 in liver metastases compared to the primary tumor." (PMID 37828574, 2023). "Addition of domatinostat to either anti-PD-1 alone or anti-PD-1 + anti-CTLA-4 significantly lowered tumor volume compared with vehicle control." (PMID 36920329, 2023).